MUC16 (mucin 16, cell surface associated)
Diseases named in the same sentence as MUC16 in open-access papers (continued):
Sharing a sentence is not in itself a finding about the gene and the disease.
ovarian carcinoma (continued). "Expectedly, MUC16 was determined to be a frequent driver fusion transcript in the ovarian cancer study by Engqvist and colleagues and was similarly prevalent in 3/9 (33%) of HGSOC patients in our cohort." (PMID 31745703, 2020). "We found that MUC16 mutant ovarian cancer samples had higher SUCNR1 expression than MUC16 wild-type samples." (PMID 33062639, 2020). "MUC1 and MUC4 overexpression induces the EMT in renal carcinoma and ovarian cancer via the Wnt/β-catenin pathway, whereas MUC16 knockdown induces EMT." (PMID 32825724, 2020). "It is overexpressed in most epithelial ovarian cancers and subsets of other cancers, and a soluble form shed into the plasma is produced by cleavage from the membrane-bound form of MUC16." (PMID 32937961, 2020). "MUC16 is overexpressed primarily in ovarian cancer with soluble, tumour-shed antigens or membrane bound forms able to suppress humoral-based immunity, particularly antibody-dependent cell-mediated cytotoxicity (ADCC)." (PMID 32937961, 2020). "Specifically, MUC16, an epithelial ovarian carcinoma antigen, is already used in clinics as a tool to diagnose ovarian cancer and it has been shown to predict lymph node metastasis with 0.78 sensitivity and specificity in EC." (PMID 32560580, 2020). "The interaction between MSLN on mesothelial cells, and MUC16 on ovarian cancer and PDAC cells was reported to favor peritoneal dissemination of tumors." (PMID 32517181, 2020). "Another unexplained junction (chr19:8865972–8876532 on the minus strand) is in the MUC16 region itself and is present in 42.8%, or 184 of 430 ovarian cancer samples." (PMID 34316681, 2020). "Secretion of MUC16 in the supernatant of HPMCs was found to be about 5-fold that of ovarian cancer cell lines." (PMID 31039761, 2019). "In a mouse xenograft model of ovarian cancer, MUC16 CAR/IL-12 T cells lengthened survival and showed increased persistence and tumor cytotoxicity." (PMID 30804938, 2019). "Heat-inactivation of ovarian cancer ascites almost completely abrogated their ability to stimulate MUC16 secretion suggesting that the MUC16-stimulating factor(s) in ascites are most likely proteins." (PMID 31039761, 2019). "More recently, in a syngeneic mouse model of peritoneal carcinomatosis (metastasized from ovarian cancer), IP-delivery of MUC16 CAR/IL-12 T cells was found to confer longer survival, even when administered to mice with significant disease progression." (PMID 30804938, 2019). "This led to the development of a phase 1 clinical trial of administering intraperitoneally IL-12 secreting MUC-16(ecto) directed CAR T cells for patients with recurrent ovarian cancer." (PMID 30736355, 2019). "As a large, heavily glycosylated molecule, MUC16 extends from the surface of ovarian cancer cells and binds to mesothelin, a protein that is found on the surface of mesothelial cells lining the peritoneum." (PMID 31514468, 2019). "There was a robust stimulation of MUC16 secretion (1.5 to 37-fold) in the conditioned medium of HPMC cultures primed with ovarian cancer ascites." (PMID 31039761, 2019). "Other notable DMGs include key markers of ovarian cancer such as MUC16 (CA-125) and PAX8, as well as genes that play key roles in ovarian cancer biology such as CCNE1 and MTHFR." (PMID 31870409, 2019). "For instance, an antibody (DUC5754A) against MUC16 has been advanced to a phase 1 clinical trial for ovarian cancer." (PMID 31822636, 2019). "In MUC16 overexpressing epithelial ovarian cancer cell lines such as OVCAR3, MUC16 expression distribution is mainly limited to the cell surface." (PMID 31039761, 2019). "Other CARs mentioned in this review that use the CD28ζ costimulatory domain include L1CAM CARs for ovarian cancer in mice, MET CARs for MPM, MUC16 CARs in mouse models of ovarian cancer and peritoneal carcinomatosis, and NKG2D CARs in Ewing's sarcoma models." (PMID 30804938, 2019). "MT1-MMP sheds mucin 16 (MUC16)/cancer antigen 125 (CA-125) from the surface of ovarian cancer cells." (PMID 31137480, 2019).
ovarian carcinoma (continued). "Cell surface MUC16 (csMUC16) is expressed by ovarian cancer cells and is detectable in the peripheral blood of cancer patients." (PMID 31143186, 2019). "Human peritoneal mesothelial cells (HPMCs) have been reported to be the major source of MUC16 found in the sera of ovarian cancer patients." (PMID 31039761, 2019). "In this context, fibrogenic TNF-α and IFN-γ stimulate the expression of MUC16 in breast, endometrial and ovarian cancers via an NF-κB response element in the MUC16 promoter." (PMID 31514468, 2019). "The start site of MUC16 transcription has been determined by 5′ Rapid amplification of cDNA ends (RACE) in ovarian cancer cell lines, and NFκB binding site is found in the region within 200 bp from the start of transcription." (PMID 29542355, 2018). "The proximity of 5E6 and 3H1 epitopes to the transmembrane domain allows these mAbs to bind to the cell surface that can be exploited for developing MUC16 targeted therapeutics for ovarian cancer." (PMID 29708979, 2018). "STn is found on a significant number of ovarian cancers and is expressed on the well-known ovarian cancer biomarker CA-125 (MUC16), as well as on MUC1, and is rarely present on normal tissue." (PMID 30052649, 2018). "MUC16 is a very large mucin (22 000 amino acid (aa)) that is heavily glycosylated and facilitates ovarian cancer." (PMID 30236127, 2018). "MUC16 is an important clinical biomarker of ovarian cancer and it is a target for various immuno-chemotherapies currently under investigation." (PMID 30287783, 2018). "Our strategy of employing monoclonal antibodies for targeting ovarian cancer cells generated specificity to cancer cells that express MUC16." (PMID 30287783, 2018). "The plasmid containing gro-α shRNA driven by this MUC16 promoter sequence decreased gro-α protein secretion in ovarian cancer cells." (PMID 29542355, 2018). "For the first time, we demonstrate that MUC16 is cleaved in ovarian cancer cells (NIH:OVCAR-3 [OVCAR-3]) and that the cleaved MUC16 subunits remain associated with each other." (PMID 29708979, 2018). "Surprisingly, mAb 5E6 exhibited intraluminal staining in some ovarian cancer cases suggesting that MUC16 CT can also be released from the cells." (PMID 29708979, 2018). "CA125 is a repeating peptide epitope of mucin MUC16 and a marker of mucin-producing malignant tumors such as ovarian cancer." (PMID 30286732, 2018). "And an interesting phenomenon was observed in this study, as a transmembrane mucin, MUC16 also expressed in the cytoplasm of ovarian cancer cell lines." (PMID 29542355, 2018). "AF(D)NMs target MUC16 antigens expressed on ovarian carcinoma cells within tumor nodules and in ascitic fluid." (PMID 30287783, 2018). "Overexpressed MUC16 is resistant to cisplatin in ovarian cancer, and cisplatin can be used to select for cisplatin-resistant cell populations." (PMID 29552305, 2018). "In this study, we developed a MUC16 promoter-driven shRNA expression vector for tumor-localized gene expression in ovarian cancer." (PMID 29542355, 2018). "The very limited expression of MUC16 in the majority of SOC cell lines was remarkable since it represents the major ovarian cancer biomarker." (PMID 30011875, 2018). "The MUC16 expression results obtained by immunocytochemistry are concordant with our findings, reporting a percentage of less than 30% of epithelial ovarian cancer cell lines positive for MUC16." (PMID 30011875, 2018). "Further, the unique location of the epitope allows the CT mAbs to bind the MUC16 CT at the cell surface, and hence can potentially be useful for targeting ovarian cancer." (PMID 29708979, 2018). "At euthanasia, MUC16 antigen expression in the ovarian carcinoma tissues significantly decreased post-treatment with the AF(D)NMs and only a few small areas of cell debris stained positive in these sections." (PMID 30287783, 2018).
ovarian carcinoma (continued). "CAR-T therapy targeting extracellular domains of MUC16, an antigen expressed on most ovarian carcinomas, have been studied in preclinical models and have shown the potential to delay progression or fully eradicate the disease in mouse models." (PMID 30421009, 2018). "High expression of TAG72, MUC1, and MUC16 has been shown in ovarian cancer patient tissue samples, with nearly 100% of ovarian cancers identified with simultaneous staining of the three antigens." (PMID 30510550, 2018). "Greater than 80% of ovarian cancer patients exhibit significantly high MUC16 expression, and CA125 (MUC16) is currently the only serum tumor biomarker routinely used for the clinical diagnosis and predictor of prognosis for ovarian cancer." (PMID 29552305, 2018). "The novel aspect of the study was the design and implementation of an antibody-functionalized nanomicelle hydrogel composite to specifically target MUC16 antigens known to be over-expressed on ovarian cancer cells." (PMID 30287783, 2018). "The implications of MUC16 in ovarian cancer provide optimal design strategies for cancer targeted therapy." (PMID 29542355, 2018). "Since TAG72, MUC1, and MUC16 have all been identified as potential targets in ovarian cancer, we first assessed expression of these cell surface antigens on TAG72-negative OVCAR8, and TAG72-positive OVCAR3 and OV90 cells." (PMID 30510550, 2018). "An ongoing clinical trial for women with ovarian cancer, using a CAR-T directed against the ovarian cancer tumor antigen MUC-16, is exploiting the natural history of the disease by infusing the cells both IP and IV." (PMID 30012146, 2018). "This work was translated into a phase I clinical trial of MUC-16 directed CARs in women with recurrent ovarian cancer that is currently ongoing (NCT02587689)." (PMID 30421009, 2018). "Here, we predicted the promoter sequences in the regions that were 4 kbp upstream of MUC16 and measured transcriptional activity in ovarian cancer cells with dual-luciferase reporter assay." (PMID 29542355, 2018). "The first clinical trial to explore the impact of IL-12 CAR-T cells has been opened by MSKCC (NCT02498912), where IL-12-secreting CAR-T cells transduced with a 28ζ CAR targeting mucin-16 (MUC-16) is being tested in patients with ovarian cancer." (PMID 28466386, 2017). "Of particular interest were MUC16 STn+‐glycoforms, characteristic of ovarian cancers, which were found in a subset of advanced‐stage bladder tumours facing the worst prognosis." (PMID 28156048, 2017). "MUC16 (CA125) is a well-known ovarian cancer marker upregulated in > 80% of cases and serves as a FDA-approved marker for ovarian relapse." (PMID 28978023, 2017). "Taking advantage of the high-affinity interaction between mesothelin and the MUC16 biomarker located on ovarian cancer cell membranes, we designed a mesothelin/TR3 fusion protein, and subsequently a more potent and stabilized truncation variant, Meso64TR3." (PMID 29267342, 2017). "The importance of MUC16 in the diagnosis, progression and therapy of ovarian cancer, and its overexpression in other cancers, demands a need for research on the regulation of this mucin." (PMID 26918940, 2016). "It turned out that OVCAR-3 cell line has the highest amount of endogenous MUC16, followed by SKBR-3 cell line, while the other ovarian cancer cell line SKOV-3 has just trace amount of MUC16." (PMID 27167110, 2016). "In this study we found that TNFα, IFNγ and MUC16 are often strongly co-expressed in endometrial, breast and ovarian cancers with cytokine staining intensity positively correlating with MUC16 staining in breast and ovarian cancers, in particular." (PMID 26918940, 2016). "Recent evidence indicate that MUC16 has been crucial in facilitating metastasis of ovarian cancer cells to peritoneum via its interaction with mesothelin." (PMID 27382435, 2016). "Similar to an epitope of MUC16, Cancer Antigen 125 (CA-125) was used in the diagnosis of ovarian cancer." (PMID 27374181, 2016).
ovarian carcinoma (continued). "The extracellular region of over-expressed MUC16 in epithelial ovarian carcinoma can be cleaved from cell surface to become circulating elements in the blood, which is a well-established ovarian cancer marker for clinical diagnosis, known as CA125." (PMID 27167110, 2016). "In vitro and in vivo studies suggested that cancer cell adhesion to the peritoneum partly relies on the interaction between MUC16 on ovarian cancer cells and mesothelin on mesothelial cells." (PMID 27074785, 2016). "Most importantly, however, when all three drugs were tested on MUC16-positive ovarian cancer cells, Meso64-TR3 was capable of eradicating nearly all target cells (92%), followed by Meso-TR3 (59%) and TR3 (14%)." (PMID 27120790, 2016). "CA125, a well known clinical tumor marker used to monitor epithelial ovarian cancer, was the cleavage fragment arising from the extracellular domain of up-regulated MUC16." (PMID 27167110, 2016). "Despite the importance of MUC16 as a biomarker in ovarian cancer and its overexpression levels in various cancers, the biological and mechanistic role of MUC16 in tumor progression and its metastatic ability has not yet been identified in pancreatic cancer." (PMID 27382435, 2016). "We therefore performed confocal microscopy following drug exposure employing the MUC16-positive ovarian cancer cell line OVCAR3." (PMID 27120790, 2016). "As MUC16 is expressed quite differently in ovary cancer cell lines SKOV-3 and OVCAR-3, we detected β-catenin in these two cell lines and found that the protein levels of MUC16 were closely correlated with that of β-catenin." (PMID 27167110, 2016). "Soon after its discovery, MUC16 was established as a serum biomarker for diagnosing and monitoring stability or progression in ovarian cancer." (PMID 26509158, 2015). "The biomarker currently used to diagnose ovarian cancer, MUC16, can only detect late stage ovarian cancer and cannot distinguish between ovarian cancers and benign ovarian diseases (BOD)." (PMID 26509158, 2015). "Overexpression of MUC16 in epithelial ovarian cancer downregulates E-cadherin and upregulates N-cadherin and vimentin, thus promoting tumor metastasis." (PMID 26356073, 2015). "In order to explore the contribution of MUC16 to the behavior of human ovarian cancer cells, we also transfected A2780 cells with the same MUC16 expression vectors, MUC16c114-GFP and MUC16c344-GFP." (PMID 25965947, 2015). "The use of carbohydrates as improved biomarkers for diagnosing ovarian cancer compared to MUC16 is currently being investigated in a clinical trial (NCT00628654)." (PMID 26509158, 2015). "We examined the role of this most proximal part of the MUC16 protein in malignant transformation and behavior in 3T3 fibroblasts and ovarian cancer cell lines." (PMID 25965947, 2015). "In June 2008, the HE4 enzyme immunoassay (EIA) test kit (Fujirebio Diagnostics, Sweden) and, in March 2010, the ARCHITECT HE4 automated version (Abbott Diagnostics, UK) were approved by the FDA as substantially equivalent to a MUC16 assay for ovarian cancer." (PMID 26509158, 2015). "Several studies have reported attempts to use MUC16 glycoforms to discriminate between endometriosis and ovarian cancer and to evaluate the clinical stage, cytological grade, and histological type of ovarian cancer." (PMID 26509158, 2015). "MUC16, precursor of the most widely used ovarian cancer biomarker CA125, is upregulated in multiple malignancies and is associated with poor prognosis." (PMID 26044153, 2015). "Serous cancers of the ovary, fallopian tube, and uterus often express large amounts of MUC16, and aberrant MUC16 expression can be found in several other malignancies, including cancers of the lung, pancreas, and breast." (PMID 25965947, 2015). "Evidence supporting the location of CA125 antigen in the MUC16 tandem repeat came from two initial studies where the tandem repeats were expressed in E. coli or in human ovarian cancer cell lines." (PMID 24886523, 2014).
ovarian carcinoma (continued). "MUC16 (CA125) is a large transmembrane mucin protein (> 200 kDa) aberrantly expressed in approximately 80% of human epithelial ovarian cancers (EOC)." (PMID 24690311, 2014). "A renewed focus on MUC16 is likely to culminate in novel and more efficient strategies for the detection and treatment of ovarian cancer." (PMID 24886523, 2014). "MUC16-mesothelin interaction allows tumor cells to bind to themselves (likely increasing tumor mass at metastatic sites) and also allows attachment of ovarian cancer cells to the mesothelial lining." (PMID 24886523, 2014). "MUC16 is not only an established biomarker in ovarian cancer, it has also been explored as a promising target for cancer therapy." (PMID 24447304, 2014). "MUC16 is an established biomarker in ovarian cancer that is also overexpressed in other malignancies such as pancreatic and breast cancers." (PMID 24447304, 2014). "In conclusion, our study examined four SNPs in MUC16 (CA125) and three SNPs in MUC1 (CA15.3) in relation to ovarian cancer risk and survival in the New England Case-Control study." (PMID 24551091, 2014). "MUC16 encodes the CA125 antigen, a diagnostic marker in ovarian cancer screening and recently reported to be altered in SLE patients, leading to the inclusion of SLE as a confounder in interpretation of CA125 screening." (PMID 25107306, 2014). "We estimate that data from 40 individuals each in the healthy control and ovarian cancer group will be required to attain 90% power to demonstrate the effect of differential MUC16 gene expression on patient survival." (PMID 24886523, 2014). "To further support the role of MUC16 in TRAIL resistance, we examined the expression of MUC16 in nine ovarian cancer cell lines." (PMID 24690311, 2014). "MUC16 protects ovarian cancer cells from naïve unstimulated NK cells as well as IL-2 stimulated NK cells." (PMID 24886523, 2014). "The high affinity ligand/receptor interaction was associated with a selective accumulation of the cancer drug on MUC16-expressing cancer targets and directly correlated with increased killing activity in vitro and in a xenograft mouse model of ovarian cancer." (PMID 24447304, 2014). "In a next step, the killing activity of Meso-TR3 on MUC16-positive cancer cells was assessed in a preclinical mouse model of ovarian cancer." (PMID 24447304, 2014). "MUC16 is also known as a potential biomarker for the following ovarian cancer after various therapies." (PMID 24722639, 2014). "Knockdown of MUC16 results in increased lysis of the ovarian cancer cells by the cytolytic NK cells." (PMID 24886523, 2014). "As the most commonly employed tumor marker, CA125/MUC16 level is frequently elevated in endometriosis and more often in ovarian cancer." (PMID 24339876, 2013). "CA125, an epitope on MUC16, is used as a tumor marker for detection of ovarian cancer in sera of patients and MUC16 influences ovarian cancer growth and metastasis." (PMID 24204560, 2013). "Although direct proof of these mechanisms is limited, it has been demonstrated that MUC16 expressed by ovarian cancer cells inhibits the formation of the immunological synapse between the tumor and NK cells." (PMID 24039759, 2013). "MUC16 is highly overexpressed in ovarian cancer and moderately overexpressed in pancreatic cancer, but the role of MUC16 in pancreatic cancer progression has not been extensively studied." (PMID 24204560, 2013). "MUC16 is used along with multiple serum biomarkers for the early detection and screening of ovarian cancer." (PMID 22481932, 2012). "Decreasing MUC16 levels are known to be of prognostic outcome in the post-operative and pre-operative neo-adjuvant chemotherapy especially in ovarian carcinoma." (PMID 22937096, 2012). "In view of the previous assertions, MUC16 needs to be probed for its plausibility as a molecular target in the immunotherapy of ovarian cancers." (PMID 22481932, 2012).